CTDSPL (CTD small phosphatase like)
Description:
Recruited by REST to neuronal genes that contain RE-1 elements, leading to neuronal gene silencing in non-neuronal cells (By similarity). Preferentially catalyzes the dephosphorylation of 'Ser-5' within the tandem 7 residue repeats in the C-terminal domain (CTD) of the largest RNA polymerase II subunit POLR2A. Negatively regulates RNA polymerase II transcription, possibly by controlling the transition from initiation/capping to processive transcript elongation.
Synonyms: hYA22; SCP3; C3orf8; PSR1; RBSP3
Tractability: Small molecule: a structure with a bound ligand is known. PROTAC: ubiquitination databases record sites on it.
Gene: Protein-coding gene on chromosome 3 (37,861,880 to 37,984,469, forward strand). Ensembl gene ENSG00000144677.
Subcellular location: Nucleus
Subcellular location (Human Protein Atlas): Vesicles; Nucleoplasm
Gene Ontology:
Molecular function: protein binding; RNA polymerase II CTD heptapeptide repeat phosphatase activity; phosphatase activity; protein serine/threonine phosphatase activity
Biological process: regulation of transcription by RNA polymerase II
Cellular component: extracellular exosome; nucleus
Genetic constraint (gnomAD): Loss-of-function variants: 3 observed, 21.02 expected, observed/expected ratio (o/e) 0.14, 90% interval 0.064 to 0.37. The upper end of that interval is the gene's LOEUF score, 0.37, which puts it in group 1 of 6, group 1 being the genes least tolerant of losing a copy. Missense variants: 210 observed, 311.84 expected, observed/expected ratio (o/e) 0.67, 90% interval 0.6 to 0.75. Synonymous variants: 98 observed, 122.29 expected, observed/expected ratio (o/e) 0.8, 90% interval 0.68 to 0.95.
Homologues: Orthologues: chimpanzee CTDSPL (100% identical), mouse Ctdspl (96% identical), rat Ctdspl (96% identical), guinea pig CTDSPL (92% identical), pig CTDSPL (91% identical), tropical clawed frog ctdspl (80% identical), macaque CTDSPL (78% identical), zebrafish ctdsplb (77% identical), zebrafish ctdspla (76% identical), Drosophila melanogaster hzg (60% identical), Caenorhabditis elegans scpl-1 (57% identical). Paralogues in human: CTDSP1 (65% identical), CTDSP2 (61% identical), CTDSPL2 (39% identical), CTDNEP1 (33% identical), TIMM50 (24% identical).
Diseases named in the same sentence as CTDSPL in open-access papers:
CTDSPL is named in the same sentence as 30 diseases in open-access papers, as found by Europe PMC text mining. Sharing a sentence is not in itself a finding about the gene and the disease. The quoted sentences say what the papers report.
acute myeloid leukemia (8 papers, 2012 to 2019). Acute myeloid leukemia (AML) is a group of neoplasms arising from precursor cells committed to the myeloid cell-line differentiation. "miR-181 family members were predicted to target CTDSPL, which had previously been denoted as RBSP3 (RB1 serine phosphatase from human chromosome 3), a key downstream mediator of cell cycle progression, and has been reported to participate in acute myeloid leukemia pathogenesis." (PMID 29382357, 2018).
prostate carcinoma (4 papers, 2007 to 2015). A carcinoma that arises from epithelial cells of the prostate gland. "We found a significant enrichment of MYC at the promoters of CTDSPL, CTDSP2 and CTDSP1 in both prostate cancer cell lines." (PMID 21941025, 2011).
uveal melanoma (4 papers, 2018 to 2025). A melanoma derived from melanocytes of the uveal tract. "The bioinformatics and functional analysis results in a study which investigated the miR-181b-5p in uveal melanoma showed that miR-181b-5p precipitated the cell cycle by targeting the CTDSPL (small phosphatase-like molecule) of the carboxy-terminal region and created an oncogenic effect." (PMID 38914847, 2025).
breast carcinoma (3 papers, 2007 to 2023). "Liu confirmed that the overexpression of miR-26a in human breast cancer cells significantly increased the expression of the host genes CTDSPL and CTDSP2, suggesting a self-perpetuating loop of miR-26a." (PMID 37373175, 2023).
B-cell lymphomas (2 papers, 2017 to 2022). "Our lab has previously identified CTDSPL (C-terminal domain small phosphatase-like) and CTDSPL2 (C-terminal domain small phosphatase-like 2) as common integration sites in ALV-induced B-cell lymphomas." (PMID 28915671, 2017). "Deep sequencing analysis of viral integration sites has identified CTDSPL and CTDSPL2 as common integration sites in ALV-induced B-cell lymphomas, suggesting a potential role in driving oncogenesis." (PMID 28915671, 2017). "We believe that the main reason integrations in CTDSPL and CTDPSL2 were selected for in B-cell lymphomas is due to the role of the truncated transcripts in immortalization." (PMID 28915671, 2017). "To better characterize the role of CTDSPL and CTDSPL2 in ALV-induced B-cell lymphomas, we generated truncated transcripts in viral vectors to mimic those being expressed in tumors." (PMID 28915671, 2017). "In this report we have identified both CTDSPL and CTDSPL2 as common integration sites in ALV-induced B-cell lymphomas." (PMID 28915671, 2017).
leukemia (2 papers, 2010 to 2013). A malignant (clonal) hematologic disorder, involving hematopoietic stem cells and characterized by the presence of primitive or atypical myeloid or lymphoid cells in the bone marrow and the blood. "In leukemia cell lines and 24% of patients with acute lymphoblastic leukemia, CTDSPL promoter is highly methylated, which promotes the occurrence of leukemia." (PMID 24191888, 2013). "Among them, CTDSPL and TRIB2 are closely associated with leukemia cell apoptosis and were chosen to be further validated in HEK-293 T cells using luciferase reporter assays." (PMID 24191888, 2013). "Finally, dual-luciferase reporter transfection assay and western blot analysis on clinical samples and leukemia cell lines further supported that miR-99a played a potential oncogene role by targeting CTDSPL and TRIB2 in most pediatric myeloid leukemia patients." (PMID 24191888, 2013).
non-small cell lung carcinoma (2 papers, 2010 to 2024). A group of at least three distinct histological types of lung cancer, including non-small cell squamous cell carcinoma, adenocarcinoma, and large cell carcinoma. "CHD5 and CTDSPL possess tumor suppressor activities in many cancers, including neuroblastomas, gliomas, and Non-Small Cell Lung Cancer (NSCLC)." (PMID 39038036, 2024).
ovarian carcinoma (2 papers, 2009 to 2012). A malignant neoplasm originating from the surface ovarian epithelium. "In some cases it was shown only decreased expression (LOC285205, EPHB1 and RBSP3 (CTDSPL)) and in other cases loss of heterozygosity and copy number changes (CGGBP1 and RBSP3 (CTDSPL)) in ovarian cancer." (PMID 23202957, 2012). "A set of eight biomarkers: NKIRAS1/RPL15, THRB, RBPS3 (CTDSPL), IQSEC1, NBEAL2, ZIC4, LOC285205 and FOXP1, was identified as the most prominent set capable to detect both early and late stages of ovarian cancer." (PMID 23202957, 2012).
chronic myeloid leukemia (1 paper, 2025). "It promotes proliferation and inhibits apoptosis in AML and chronic myeloid leukemia (CML) cells by targeting CTDSPL and TRIB2." (PMID 40161350, 2025).
kidney tumors (1 paper, 2023). "CTDSPL inactivation in kidney tumors may be mediated by mechanisms different from CTDSP1 and CTDSP2." (PMID 37629167, 2023).
lymph node metastases (1 paper, 2019). "There is only a slight association between CTDSPL expression and the presence of lymph node metastases (rs = – 0.1, P=0.02) in the case of ADC." (PMID 31774910, 2019). "In addition, we showed a clear difference of the CTDSP1, CTDSPL and RB1 relative mRNA levels in ADC with and without lymph node metastases, but not in SCC (P≤0.05)." (PMID 31774910, 2019).
lymphoma (1 paper, 2011). A malignant (clonal) proliferation of B- lymphocytes or T- lymphocytes which involves the lymph nodes, bone marrow and/or extranodal sites. "Myc was previously reported to regulate the expression of miRNAs, including miR-26a and miR-26b in P493 lymphoma cells, by direct binding to their host Pol II gene promoters (CTDSPL, CTDSP2, CTDSP1)." (PMID 21941025, 2011).
melanoma (1 paper, 2018). A malignant, usually aggressive tumor composed of atypical, neoplastic melanocytes. "Our work found that miR-181b is overexpressed in melanoma tissues and most UM cells and promotes cell cycle progression by repressing CTDSPL expression in UM cells." (PMID 29382357, 2018).
myeloid leukemia (1 paper, 2013). A clonal proliferation of myeloid cells and their precursors in the bone marrow, peripheral blood, and spleen. "A current research showed that CTDSPL relates to the regulation of cell growth and differentiation, and frequent mutations or deregulation of this gene are disclosed in human hematopoietic cell and myeloid leukemia cell lines." (PMID 24191888, 2013). "In conclusion, our study indicates that miR-99a may play an oncogenic role by targeting the tumor suppressors CTDSPL and TRIB2 in most pediatric myeloid leukemia." (PMID 24191888, 2013).
tumor (19 papers, 2005 to 2024). "Disease-free survival analysis also showed an association of lower CTDSPL expression with a shorter time to tumor recurrence (p < 0.001, log-rank test)." (PMID 37629167, 2023). "The correlation of CTDSPL downregulation with poorer survival in ccRCC patients also suggests that this gene is associated with tumor malignancy." (PMID 37629167, 2023). "CTDSPL has been implicated as a tumor suppressor gene, and its expression is suppressed or lost in many cancer cell lines." (PMID 22523603, 2012). "Among that, the protein expression of IGF2BP3, B2M, CD36, CDKN1A, ANKRD33B, and LHFPL2 were up-regulated; However, the protein expression of APP and CTDSPL was low in both normal and tumor tissues." (PMID 39470474, 2024). "Owing to the frequent mutation, the expression of CTDSPL has been impaired in many epithelial tumors, indicating a tumor-suppressor role of CTDSPL." (PMID 38460957, 2024). "Despite this, a noticeable decrease in expression was found in primary tumor samples only for the CTDSPL gene in our sampling." (PMID 37629167, 2023). "CTDSP2 and CTDSPL also inhibit tumor growth and angiogenesis through dephosphorylation of RB and tumor-suppressor protein promyelocytic leukemia (PML)." (PMID 32397221, 2020). "Altogether, these data suggest tumor suppressor activity of CTDSPL, CTDSP1, and CTDSP2 genes in different types of cancer." (PMID 31774910, 2019). "The tumor suppressor property of CTDSPL is related to its ability to remove the phosphate group from serine 807 and 811, and induce the formation of the RB-E2F1 complex." (PMID 24191888, 2013). "As the function of the CTDSPL gene product remains unclear, further analyses of CTDSPL will be necessary to solve the apparent contradiction between our findings and the reported tumor suppressor function." (PMID 22523603, 2012). "Therefore, the up-regulation of miR-26a/b in old UCMSCs inspired us to analyze whether their host gene CTDSPL, which was previously identified as a tumor-suppressor gene, was up-regulated in the late passage of UCMSCs." (PMID 38460957, 2024). "This, in addition to the observation that integrations in CTDSPL and CTDSPL2 occur in both primary and secondary tumors, suggests a potential role in promoting tumor metastasis." (PMID 28915671, 2017). "Considering that senescence is an important anti-tumor mechanism in mammalian cells, it was not surprising to find that the up-regulation of CTDSPL significantly induced senescence of UCMSCs." (PMID 38460957, 2024). "Our data confirmed that CTDSP1 and CTDSPL (but not CTDSP2) exerts tumor suppressive activity in ccRCC." (PMID 37629167, 2023). "Additionally, the functionality of CTDSP2 and CTDSPL, such as their catalytic activity against RNAP II CTD peptide and their tumor-suppressing role, also overlaps with that of CTDSP1." (PMID 32397221, 2020). "The tumor suppressor properties of CTDSP2 and CTDSPL has also been reported in recent studies." (PMID 32397221, 2020). "Interestingly, integrations in CTDSPL and CTDSPL2 frequently occur in the same tumor." (PMID 28915671, 2017). "Additionally, dual-luciferase reporter transfection assay and western blot analysis indicated that miR-99a may target CTDSPL and TRIB2, which are two tumor suppressor genes." (PMID 24191888, 2013). "These genes include tumor suppressors or candidates (VHL, CTDSPL, LRRC3B, ALDH1L1, and EPHB1) and genes that were not previously considered as cancer-associated (e.g., LRRN1, GORASP1, FGD5, and PLCL2)." (PMID 24977159, 2014).
cancer (16 papers, 2007 to 2026). A tumor composed of atypical neoplastic, often pleomorphic cells that invade other tissues. "Regarding these, the miR-181 family is reported to promote the endothelial and cancer cell cycle by targeting CTDSPL." (PMID 34746267, 2021). "In silico and data-mining analyses suggest that FAM171A1 has been predicted to interact with FAM171B, PCDHGB1, TNFRSF17, TMEM, CTDSPL, and NTRK1, many of which have been already implicated in various cancers suggesting most likely its possible role in the tumorigenesis." (PMID 30631046, 2019). "Our work suggests that CTDSPL and CTDSPL2 play a role in cancer and seem to have pro-oncogenic characteristics." (PMID 28915671, 2017). "Genes labeled by IPA as being cancer related (COL18A1, STAT5B, CTDSPL) were also involved with infection as were genes involved in apoptosis and growth (CTDSPL, POLR2F, ZBTB16)." (PMID 18047719, 2007).
CTDSPL also shares sentences with these, for which no sentence is quoted: infection (6 papers); lung carcinoma (3); cervical cancer (2); acute lymphoblastic leukemia (1); adenocarcinoma (1); breast tumors (1); glioma (1); neuroblastoma (1); Prader-Willi syndrome (1); prostate tumors (1); schizophrenia (1); small cell lung carcinoma (1); squamous cell carcinoma (1); uterine serous carcinoma (1).